SPP1 (secreted phosphoprotein 1)
Diseases named in the same sentence as SPP1 in open-access papers (continued):
Sharing a sentence is not in itself a finding about the gene and the disease.
colorectal cancer (155 papers, 2006 to 2026). A primary or metastatic malignant neoplasm that affects the colon or rectum. "Corresponding studies also pointed out that SPP1+ macrophages are metastasis accelerators of colorectal cancer and are associated with cell senescence, leading to poor prognosis in tumor patients." (PMID 40062730, 2025). "SPP1+ macrophages have been implicated in the progression of and poor outcomes for colorectal cancer patients." (PMID 38611120, 2024). "In a recently constructed single-cell sequencing-based colorectal cancer myeloid cell atlas, a subtype of TAMs derived from monocyte-like cells, known as SPP1+ TAMs, was discovered to be associated with a poorer prognosis." (PMID 38888512, 2024). "Meanwhile, SPP1+ TAMs have been proved to be characterized by their tumor promoting activities and are associated with metastasis in colorectal cancer." (PMID 39507421, 2024). "High SPP1 expression has previously been shown to be associated with poor overall survival in colorectal cancer, with increasing expression from normal tissue to primary tumors and ultimately to metastases." (PMID 38706595, 2024). "A significant correlation has been identified between SPP1-expressing TAMs and protumor activation of cancer-associated fibroblasts (CAFs) in colorectal cancer, suggesting SPP1 as a factor in cell-to-cell communications between TAMs and CAFs." (PMID 37190178, 2023). "In liver and colorectal cancers, SPP1+ macrophages were associated with tumor pro-angiogenesis and prognosis and were specifically present in metastatic colorectal cancer but not metastatic liver cancer." (PMID 36569953, 2022). "The expression of SPP1+ tumor-associated macrophages has previously been identified in eight other tumor types, including colorectal cancer and breast cancer." (PMID 36180422, 2022). "It was demonstrated that overexpression of SPP1 was closely associated with tumor invasion, metastasis and low survival in colorectal cancer." (PMID 31304688, 2019). "The association between SPP1 expression and recurrence status was evaluated in 166 patients with colorectal cancer who were treated with FOLFOX." (PMID 29957058, 2019). "As well as extensive circumstantial data associating high SPP1 expression in human colorectal cancer, Spp1 was also previously reported to be a key Smad4 dependent expressed gene functionally associated with murine prostatic cancer invasion in a Pten prostate deletion model." (PMID 40348815, 2025). "Both molecules are associated with colorectal cancer progression, where SPP1 might promote cancer cell migration and invasion and where IL6 is a pro-inflammatory cytokine that may promote cancer cell proliferation and survival." (PMID 40895532, 2025). "Additionally, research in colorectal cancer found that SPP1+ macrophages are associated with suppressed T cell infiltration in the TME, with a higher presence of SPP1+ macrophages correlating with less benefit from immunotherapy." (PMID 38600248, 2024). "Colorectal cancer metastases in the liver could establish immunosuppressive spatial networking between tumor-associated SPP1+ macrophages and fibroblasts, which supported colorectal cancer growth in the immunosuppressed metastatic niche in the liver." (PMID 38347955, 2023). "In primary human and mouse colorectal cancer samples, mTORC2 is only expressed in the adjacent area of macrophages, but not in tumor cells, as mTORC2-deficient macrophages stimulate tumor growth through the cytokine SPP1/osteopontin." (PMID 37875976, 2023). "The molecular analysis demonstrated that SPP1 gene amplification was the highest genetic alteration of SPP1 across many cancer types, whereas the frequency of SPP1 mutation (missense mutation) was low in bladder cancer compared to uterine, skin, lung, cervical, gastric and colorectal cancers." (PMID 38067407, 2023). "SPP1 linked with lung adenocarcinoma, gastric cancer and colorectal cancer." (PMID 34116656, 2021).
colorectal cancer (continued). "In addition, SPP1 could promote the progression of ovarian cancer and cause poor survival outcomes in colorectal cancer." (PMID 36873244, 2023). "In IPF, SPP1+ macrophages are highly expanded in fibrotic lesions and cross talk with myofibroblasts to drive fibrotic changes; in colorectal cancer, there are direct interactions between SPP1+ macrophages and FAP+ fibroblasts expressing high levels of MMP1/3." (PMID 41489684, 2026). "In colorectal cancer, not only is OPN/Spp1 expression higher in malignant tissue but is also associated with poor survival and metastasis through EMT." (PMID 40865052, 2025). "Specifically, in liver metastases of patients with poor-outcome colorectal cancer, Spp1 was significantly higher and enriched in TAM populations with EMT signatures." (PMID 40865052, 2025). "The intercellular network between SPP1+ macrophages and fibroblasts supports the growth of colorectal cancer in the liver immunosuppressive metastatic microenvironment, providing a potential target for immune checkpoint‐resistant microsatellite stable tumors." (PMID 40062730, 2025). "Through spatial multiomics, it is revealed that SPP1+ fibroblasts play a pivotal role in determining metabolic heterogeneity and promoting metastatic growth of colorectal cancer liver metastasis." (PMID 41294857, 2025). "A recent study of colorectal cancer highlighted the infiltration of senescent tumour cells around SPP1+ macrophages with remarkable SASP features." (PMID 39231761, 2025). "The interaction of SPP1+ TAMs with fibroblasts establishes an immunosuppressive metastatic niche, fostering the growth of colorectal cancer cells within this niche." (PMID 40034694, 2025). "have demonstrated that HLA‐G+ tumour cells infiltrating the colorectal cancer border orchestrate the transformation of neighbouring macrophages into SPP1+ macrophages, thereby shaping a distribution gradient." (PMID 39350478, 2024). "Among the identified genes, SP5, SIX4, TREX2, and SPP1 were upregulated and were adverse prognostic factors in colorectal cancer." (PMID 39309424, 2024). "Our SPP1+ TAM population also expressed CD68 but had low expression of CD206 and CD163, which differed slightly from another study of SPP1+ macrophages in colorectal cancer that had high CD206 expression." (PMID 39075108, 2024). "Single-cell RNAseq analysis of colorectal cancer samples revealed that the SPP1-positive population of TAMs was strongly enriched in the tumor angiogenesis, ECM receptor interaction, and tumor vascularisation pathways." (PMID 39516356, 2024). "Recently, C1q and SPP1 emerged as suitable surface markers to distinguish Mph subsets in colorectal cancer." (PMID 38500875, 2024). "For example, targeting the interaction between SPP1+macrophages and fibroblasts can enhance immunotherapy response in colorectal cancer." (PMID 38515213, 2024). "Colorectal cancer cells at the invasive front play a role in transforming macrophages into SPP1+ macrophages." (PMID 39350478, 2024). "Studies have shown that SPP1+macrophages promote colorectal cancer cell proliferation and limit T cell infiltration, and their increased proportion in the TME is associated with worse patient prognosis." (PMID 39238647, 2024). "In our investigation, RT-q PCR was utilized to ascertain the expression levels of C5AR1, APOE, CYP1B1, and SPP1 in a standard colon cell line and three colorectal cancer cell lines." (PMID 39494300, 2024). "The reciprocity of FAP+ fibroblasts and SPP1+ macrophages has been revealed through single-cell and spatial analysis in colorectal cancer (CRC)." (PMID 37143134, 2023). "Recently, single cell spatial analysis revealed the intricate relationship between FAP+ fibroblasts and SPP1+ macrophages in colorectal cancer patients." (PMID 37035187, 2023).
colorectal cancer (continued). "In colorectal cancer, SPP1-expressing TAMs were located in the invasive front, and the SPP1 signal was suggested to be involved with cancer cell expression of HLA-G, which in turn was associated with cancer cell escape from the immune system." (PMID 37190178, 2023). "The interaction of SPP1+ macrophages with FAP+ fibroblasts also appeared in colorectal cancer to promote metastasis." (PMID 38347955, 2023). "In concordance with our data, reduced expression of SPP1 was reported as an unfavorable prognosticator in both colorectal cancer and endometrial carcinoma." (PMID 38067407, 2023). "SPP1 can act as a hub gene for methylation and enhance colorectal cancer (CRC) metastasis through the mesenchymal transition in CRC cell lines." (PMID 37165402, 2023). "In colorectal cancer, patients with high SPP1 expression achieved less therapeutic benefit from an anti-PD-L1 therapy cohort." (PMID 37158834, 2023). "Consistent with these reported functions of SPP1 and macrophages in the SPP1+ state, stratification of colorectal cancer TCGA transcriptomes by SPP1 signature enrichment reveals significant reductions in patient survival when tumors have high SPP1 signature." (PMID 38036590, 2023). "SPP1-expressing macrophages have been demonstrated to influence the invasive potential of colorectal cancer cells via HLA-G." (PMID 38067407, 2023). "For instance, the immunotherapeutic effect of colorectal cancer patients with high expression of SPP1 is closely related." (PMID 37723560, 2023). "In colorectal cancer, SPP1 expression was significantly upregulated, and it promoted CRC metastasis by activating the epithelial-mesenchymal-transition pathway." (PMID 37122535, 2023). "Upregulated SPP1 expression can promote the metastasis of colorectal cancer, and SPP1 inhibition can improve the cisplatin chemosensitivity of cervical cancer." (PMID 36266702, 2022). "Another single-cell and spatial analysis revealed interaction of FAP + fibroblasts and SPP1 + macrophages in colorectal cancer, and their presence is negatively correlated with lymphocyte infiltration and predicted a poor patient survival." (PMID 36585688, 2022). "FAP+ fibroblasts and SPP1+ macrophages are the major components of TME in colorectal cancer, which are characterized as major contributors to the desmoplastic tumor structure and immunotherapy resistance against PD-L1 in colorectal cancer." (PMID 35898884, 2022). "SPP1 expression is related with poor survival in colorectal cancer patients with positive venous invasion and advanced TNM stage." (PMID 36059672, 2022). "In colorectal cancer patients, SPP1 induces high expression of CD44v6 through the Wnt-β-catenin pathway to stimulate cancer progression." (PMID 35154316, 2022). "SPP1 expression correlates with poor prognosis in many cancer types, including biliary cancer, and SPP1+ TAMs have been identified in other CPI-insensitive diseases including colorectal cancer." (PMID 36130508, 2022). "Secreted phosphoprotein 1 (SPP1) expression level was correlated with tumor stage and aggressiveness in several cancers, including colorectal cancer." (PMID 35328635, 2022). "Despite the existence of multiple well-characterized colorectal-cancer-associated macrophage subgroups, including C1QC+ TAMs, SPP1+ TAMs, and FCN1+ TAMs, we identified a kind of tumor-resident FOLR2+ LYVE1+ macrophage subgroup in colorectal cancer." (PMID 36172359, 2022). "SPP1 expression was significantly up-regulated in colorectal cancer, and it promoted the cells invasion and metastasis of colorectal cancer by activating EMT process." (PMID 36266702, 2022). "One study indicates that SPP1 activates JNK signaling through a CD44v6-dependent pathway to promote clonogenicity of colorectal cancer cells, and the CD44v6 antibody is able to potently block the activation of JNK induced by SPP1." (PMID 34676217, 2021).
colorectal cancer (continued). "FABP6, hypermethylated SFRP1, XDH, PLAU, ADH1C, HSD17B2, and SPP1 have been identified more as a colorectal cancer biomarker than as a therapeutic target at present." (PMID 34381520, 2021). "In colorectal cancer, high SPP1 expression is correlated with poor survival, high TNM stage and positive venous invasion." (PMID 33954053, 2021). "As in colorectal cancer, elevation of SPP1 expression was localized to and globalized across myeloid cell states, with all sub-clusters showing increased SPP1 levels." (PMID 33670921, 2021). "Noteworthily, silencing of SPP1 in epidermal cells increased the chemoattractant effect of epidermal growth factor (EGF), and overexpression of microRNA miR-27a reduced SPP1 levels, leading to a promotion of colorectal cancer." (PMID 34357010, 2021). "More evidence shows that SPP1 was overexpressed in various types of cancers and contributes to the occurrence and development of tumors, including colorectal cancer, cervical cancer, gastric cancer, and so on." (PMID 33968738, 2021). "Consistently, mice with the myeloid-specific deletion of mTORC2 were more susceptible to colitis-associated colorectal cancer (CAC) exhibiting an enhanced production of inflammatory mediators, including SPP1/osteopontin." (PMID 34831183, 2021). "Under physiological conditions, the transcription factor IRF8 represses myeloid-derived SPP1 expression; however, in the murine colorectal cancer microenvironment, forced loss of IRF8 led to enhanced production of SPP1 by PMN-MDSCs and tumour cells." (PMID 33187209, 2020). "SPP1, located at 4q22.1, is overexpressed in different malignant neoplasms including medullary thyroid cancer, colorectal cancer, and HCC and plays a role in metastasis and tumorigenesis 43-45." (PMID 31695766, 2019). "RNA expression levels of secreted phosphoprotein 1, the gene that encodes OPN, correlate with poor prognosis in patients with colorectal cancer and are elevated in chemotherapy-treated patients who experience tumor recurrence vs. no recurrence." (PMID 29957058, 2019). "We also examined SPP1 gene expression in patients with colorectal cancer who have received FOLFOX therapy, a commonly used cocktail of 3 agents (leucovorin, 5-FU, and oxaliplatin)." (PMID 29957058, 2019). "Not only is SPP1 expression higher in colorectal cancer cell lines than normal intestinal cell lines, but it is higher in tumor tissue in comparison to normal tissue." (PMID 25751518, 2015). "SPP1+ macrophages have been identified as key players in the colorectal cancer (CRC) tumor microenvironment, but their function remains unclear." (PMID 40092488, 2025). "Single-cell spatial multiomics suggests SPP1+ fibroblasts may drive metabolic variation and support colorectal cancer liver metastasis." (PMID 41294857, 2025). "Despite the correlation established for Spp1 and Pak3 in mouse adenoma organoids, these two genes did not appear significantly differentially expressed in human colorectal cancer with respect to SMAD4 variants." (PMID 40348815, 2025). "Similarly, in lung and colorectal cancers, elevated SPP1 expression correlates with the enrichment of M2-like TAMs, which secrete immunosuppressive cytokines such as IL-10 and TGF-β, further dampening antitumor immunity." (PMID 41391064, 2025). "Notably, in high-risk colorectal cancer (CRC) patients, an increased abundance of SPP1 + macrophages correlates with an immunosuppressive TME, facilitating immune evasion and metastatic dissemination." (PMID 41391064, 2025). "Additionally, stClinic identifies a niche abundant in SPP1+ MTRNR2L12+ myeloid cells and cancer-associated fibroblasts driving colorectal cancer cell adaptation and invasion in healthy liver tissue." (PMID 40523901, 2025). "Additionally, SPP1 expression is positively related to CD86, which is associated with M2-type macrophages in colorectal cancer." (PMID 38919629, 2024).
colorectal cancer (continued). "In colorectal cancer, the SPP1+ Mφ were positively correlated with the tumor-specific FAP+ fibroblasts, and the high infiltration of SPP1+ Mφ and FAP+ fibroblasts was associated with poor anti-PD-L1 therapeutic effects, highlighting the important role of SPP1 in cancer development." (PMID 39691723, 2024). "In colorectal cancer, SPP1+ macrophages highly express complement component 1C chain (C1QC), mannose receptor C type 1 (MRC1), signal transducer and activator of transcription 1 (STAT1), and peroxisome proliferator-activated receptor gamma (PPARG), which are associated with macrophage polarization." (PMID 38919629, 2024). "Notably, SPP1+ macrophages have been shown to interact with FAP+ fibroblasts in colorectal cancer and can stimulate the generation of desmoplastic structures limiting T-cell infiltration." (PMID 39400127, 2024). "The association of SPP1 upregulation with TAMs also confirms our previous finding, made using CODEX, of a SPP1+ pro-fibrogenic TAM cell state in liver metastases, and the finding of a SPP1+ TAM cell state in primary colorectal carcinoma." (PMID 38217002, 2024). "Thus, we demonstrated high prognostic significance of angiogenesis-associated factors S100A4, SPP1 and SPARC that are produced by TAMs in colorectal cancer." (PMID 36895491, 2023). "Studies also found that SPP1+macrophages were metastasis accelerators of colorectal cancer." (PMID 38347955, 2023). "CD44v6, a functional variant of CD44, was overexpressed on cancer cells located in the invasive front of colorectal cancer, and SPP1-expressing TAMs interacted with CD44v6-postive cancer cells, indicating the significance of SPP1/CD44v6 binding in cancer progression." (PMID 37190178, 2023). "It has been suggested that the interactions between FAP+ CAFs and SPP1+ macrophages could promote the formation of a desmoplastic TME in colorectal cancer." (PMID 38115703, 2023). "In a single-cell and spatial atlas of colorectal cancer liver metastasis, SPP1+ macrophages were specifically present in liver metastatic tumors and responsive neoadjuvant chemotherapy (NAC) could downregulate this subset of macrophages." (PMID 35558087, 2022). "Single-cell RNA sequencing (scRNA-seq) analysis from colorectal cancer patients showed that SPP1+ TAMs expressing syndecan-2 (SDC2) were more likely to interact with CAFs expressing MMP-2 through the combination of SDC2 and MMP-2 to promote the activation of CAFs and tumor tissue fibrosis." (PMID 35898884, 2022). "SPP1, a key extracellular matrix protein, is involved in colorectal cancer migration and invasion." (PMID 36532065, 2022). "FAP+ fibroblasts and SPP1+ macrophages were mostly enriched in tumor tissue, and a high correlation between the infiltration of MSCs and myeloid cells was found in patients across 14 colorectal cancer datasets." (PMID 35365629, 2022). "In multiple malignant tumors such as gastric, esophageal, and colorectal cancers, SPP1 could be detected to have a significantly high expression." (PMID 32595698, 2020). "To examine OPN expression in patients with colorectal cancer, we examined samples from patients with colon adenocarcinoma and rectum adenocarcinoma using data from The Cancer Genome Atlas to analyze the correlation between expression of SPP1 RNA and survival." (PMID 29957058, 2019). "In colorectal cancer (CRC), SPP1, C5AR1, MMP3, TIMP1, and ADAM8 were validated as macrophage-related biomarkers influencing tumor progression." (PMID 40422244, 2025). "In colorectal cancer (CRC), interactions between SPP1+ macrophages and FAP+ fibroblasts, mediated by macrophage-derived factors such as TGFB1 and IL1A/B drive the development of a fibrotic barrier along the tumor margin." (PMID 41425545, 2025). "This shows that both FAP+ fibroblasts and SPP1+ macrophages are largely responsible for orchestrating the TME and they should be considered as a potential target for colorectal cancer." (PMID 37035187, 2023).